NR2F1 (nuclear receptor subfamily 2 group F member 1)
Diseases named in the same sentence as NR2F1 in open-access papers (continued):
Sharing a sentence is not in itself a finding about the gene and the disease.
hearing loss (2 papers, 2013 to 2025). "The overlap of a long-range chromatin loop between the Mctp1 and the Nr2f1 with a known hearing loss-associated deletion (dwnd_deletion) provides evidence that structural variants can disrupt enhancer-promoter interaction, leading to Nr2f1 dysregulation, even in the absence of coding mutations." (PMID 41169613, 2025). "Beyond NR2F1 and DLX5/6, our map offers a general platform for investigating enhancer-driven mechanisms in hearing loss." (PMID 41169613, 2025). "This high-resolution view allowed us to identify enhancer-promoter interactions at critical loci, including NR2F1 and DLX5/6, both of which are linked to hearing loss." (PMID 41169613, 2025). "We focused on two cochlea disease-linked regions, NR2F1 and DLX5/6, because disease-associated structural variants overlap their loop anchors, providing an opportunity to examine how disruptions at these sites could reshape chromatin organization and impair gene regulation in hearing loss." (PMID 41169613, 2025).
Lymph Node Metastasis (2 papers, 2022 to 2024). "Conversely, NR2F1 expression was higher in the group with lymph node metastasis in three out of four cohorts." (PMID 35740627, 2022). "Furthermore, NR2F1 expression was detected to be significantly increased in BC tissues, especially in patients with lymph node metastasis." (PMID 39219375, 2024). "Among the CAF types, NR2F1 expression was higher in inflammatory CAF than in myofibroblastic CAF as well as in larger-size tumors and tumors with lymph node metastasis." (PMID 35740627, 2022). "Meanwhile, compared with BC patients without lymph node metastasis, NR2F1 was signally upregulated in BC patients with lymph node metastasis (*p < 0.05)." (PMID 39219375, 2024). "Conversely, in CAFs, NR2F1 expression was higher in T3 or tumors with lymph node metastasis, TGFB1 was higher in larger T categories or without lymph node metastasis, and there was little difference in SOX9 expression." (PMID 35740627, 2022).
megacolon (2 papers, 2016 to 2023). "The transcription factor regulatory network revealed that fibrosis‐related and megacolon‐related NR2F1 in the fibroblasts and glial subsets was up‐regulated in the aganglionic segment." (PMID 36738110, 2023).
Nystagmus (2 papers, 2020 to 2021). Rhythmic, involuntary oscillations of one or both eyes related to abnormality in fixation, conjugate gaze, or vestibular mechanisms. "The patient (Proband No. 27) with NR2F1 nonsense variant had visual loss and nystagmus since the age of 8 years." (PMID 34573359, 2021).
osteosarcoma (2 papers, 2018 to 2022). A usually aggressive malignant bone-forming mesenchymal neoplasm, predominantly affecting adolescents and young adults. "In “Pericyte”, differentially expressed NRs such as NR4A1, NR3C1, NR2F2, NR2F1, NR1H2, and ROR were detected among metastasis, primary, and recurrent osteosarcoma tissues." (PMID 35965537, 2022).
prostate tumor (2 papers, 2012 to 2025). "Expression of the orphan nuclear receptor subfamily 2 group F member 1 (NR2F1, also known as COUP-TFI) promotes tumor cell dormancy via induction of SOX9/RAR/TGF/p38-driven quiescence programs in breast and prostate tumor models; however, the role of NR2F1 in drug tolerance remains unknown." (PMID 40955663, 2025).
Anxiety (1 paper, 2023). Intense feelings of nervousness, tension, or panic often arise in response to interpersonal stresses. "In the mature hippocampus, the expression of Nr2f1 is higher in the dorsal hippocampus, which is related to spatial learning and memory, and the expression of Nr2f2 is mainly in the ventral hippocampus, which is associated with emotion and anxiety (a)." (PMID 37751231, 2023).
autosomal dominant optic atrophy (1 paper, 2022). An autosomal dominant hereditary condition characterized by optic atrophy and progressive visual loss. "These include an Ethe1−/− model of ethylmalonic encephalopathy (EE), a Tymp−/− model of mitochondrial neuro-gastrointestinal encephalo-myopathy (MNGIE), and Nr2f1−/− and OPA1delTTAG models for autosomal dominant optic atrophy (ADOA, BBSOA) as well as an Ndufs4−/− model of Leigh syndrome." (PMID 35203486, 2022).
cataract (1 paper, 2025). Partial or complete opacity of the crystalline lens of one or both eyes that decreases visual acuity and eventually results in blindness. "Collectively, these findings indicate that NR2F1 represents a promising therapeutic target for treating fibrotic cataracts." (PMID 40641526, 2025). "Future studies in this line of inquiry should extend their scope to investigate the influence of the NR2F1 gene on various cataract subtypes." (PMID 40641526, 2025). "Interestingly, we observed a significant up-regulation of NR2F1 protein in the anterior subcapsular cataract mice model and transforming growth factor-β1 (TGF-β1)-treated SRA01/04 cells." (PMID 40641526, 2025). "However, our investigation focused primarily on the role of NR2F1 in a specific subset of cataracts, and other prevalent types remain unexplored." (PMID 40641526, 2025). "In conclusion, our study suggests that NR2F1 is related to EMT in cataracts." (PMID 40641526, 2025). "Additionally, we explored the effect of NR2F1 in an animal model and cells; however, the role of NR2F1 in cataract patients remains unclear." (PMID 40641526, 2025). "Mechanistically, dual-luciferase experiments revealed that NR2F1 bound directly to the promoter of STAT3 and regulated the expression of p-STAT3, resulting in the development of cataracts." (PMID 40641526, 2025). "Mechanically, NR2F1 proteins directly interacted with the promoter region of STAT3 and orchestrated the up-regulation of phosphorylated STAT3 (p-STAT3), thereby facilitating the apoptosis and migration of SRA01/04 cells via the JAK1/STAT3 pathway, resulting in epithelium fibrosis and cataracts." (PMID 40641526, 2025).
chronic hepatitis (1 paper, 2015). An active inflammatory process affecting the liver for more than six months. "Moreover, NR4A1 and NR2F1 are soluble nuclear hormone receptors that regulate liver development, differentiation and function, and are implicated in the modulation of the hepatocyte priming and proliferation in regenerating liver, chronic hepatitis and HCC development." (PMID 26226632, 2015).
coloboma (1 paper, 2022). An abnormality in which a part of a structure in one or both eyes is missing. "By homology, data from Nr2f1 mouse models showed delayed ventral fissure closure in null embryos or severe coloboma in double Nr2f1 and Nr2f2 conditional mutants, suggesting that impaired ventral fissure fusion could be responsible for OD malformations in a Nr2f1-deficient context." (PMID 35455940, 2022). "The involvement of Pax2 in an Nr2f1-regulated network is particularly important, as human PAX2 mutations lead to coloboma-like OD malformations in the context of syndromic conditions, consistent with a key role of the Nr2f1-Pax2-Pax6 genetic network for the correct establishment of the OD region." (PMID 35455940, 2022).
colorectal cancer (1 paper, 2021). A primary or metastatic malignant neoplasm that affects the colon or rectum. "Tob phosphorylation also contributes to the progression of PTC and NR2F1-AS1identified as a hub gene by us could suppress proliferation of colorectal cancer cells by regulating TOB1." (PMID 34721037, 2021).
cutaneous melanoma (1 paper, 2025). A primary melanoma arising from atypical melanocytes in the skin. "Together, these data associate NR2F1 upregulation with drug tolerance and MRD following targeted therapy in cutaneous melanoma." (PMID 40955663, 2025).
esophageal squamous cell carcinoma (1 paper, 2024). Esophageal squamous cell carcinoma (ESCC) is a type of esophageal carcinoma (EC) that can affect any part of the esophagus, but is usually located in the upper or middle third. "For example, NR2F1 interacted with NR2F1-AS1 to activate the Sonic Hedgehog signaling pathway and promote the progression of esophageal squamous cell carcinoma." (PMID 39311119, 2024).
Hydrocephalus (1 paper, 2022). Hydrocephalus is an active distension of the ventricular system of the brain resulting from inadequate passage of CSF from its point of production within the cerebral ventricles to its point of absorption into the systemic circulation. "However, it still remains to be verified that NR2F1 is associated with hydrocephalus using a lot of clinical data or related animal research results." (PMID 36221391, 2022).
learning disorders (1 paper, 2019). "To understand whether Nr2f1 heterozygotes encountered similar associative visual and learning disorders, we tested their performance firstly in a light‐dependent operant conditioning task and later in the same box, but with a cue depending on a small light bulb switched on or off." (PMID 31318166, 2019).
leiomyoma (1 paper, 2007). A well-circumscribed benign smooth muscle neoplasm characterized by the presence of spindle cells with cigar-shaped nuclei, interlacing fascicles, and a whorled pattern. "They included several genes such as NR2F1, PNN, Smad4, Smad5, STAT5B, JUN, TGIF2, and ATF1 that were over-expressed while RUNX3, STAT1, STAT6, EGR3, GAS7, Smad1, and EDF1 were underexpressed in leiomyomas as compared to keloid/incisional scars." (PMID 17718906, 2007).
metastatic disease (1 paper, 2022). "When NR2F1 expression is associated with metastatic disease, it is of interest to study its relationship with clinical outcomes." (PMID 35740627, 2022).
neuropathy (1 paper, 2019). A disorder affecting the nervous system that manifests with pain, tingling, numbness, and/or muscle weakness. "The recently described Bosch‐Boonstra‐Schaaf optic atrophy (BBSOA) syndrome denotes an autosomal dominant genetic form of neuropathy caused by mutations or deletions in the NR2F1 gene." (PMID 31318166, 2019). "Our findings show that Nr2f1 mutant mice can be used as a model to reproduce the BBSOA syndrome and, more broadly, can serve as a tool to test possible therapeutic approaches aimed at counteracting ON neuropathies." (PMID 31318166, 2019). "Overall, we show that Nr2f1 mutant mice can be used as a model to reproduce the BBSOA syndrome and, more broadly, could serve as a tool to test possible therapeutic approaches aimed at counteracting ON neuropathies." (PMID 31318166, 2019).
pancreatic cancer (1 paper, 2024). "In pancreatic cancer, increased NR2F1 resulted in promoted cancer cell biological behaviours, including proliferation, migration, and invasion." (PMID 39219375, 2024).
psoriasis (1 paper, 2021). An autoimmune condition characterized by red, well-delineated plaques with silvery scales that are usually on the extensor surfaces and scalp. "In spite that these results must be validated in vitro and in vivo with a functional genomics approach, we propose FOXP2, RUNX2, NR2F1, ELF1 and HESX1 transcription factors (those with the highest FIF on each gene) as novel drug targets for psoriasis." (PMID 33898962, 2021).
pulmonary fibrosis (1 paper, 2023). Chronic progressive interstitial lung disorder characterized by the replacement of the lung tissue by connective tissue, leading to progressive dyspnea, respiratory failure, or right heart failure. "Transcription factor NR2F1 protein was involved in regulating ECM expression and tissue fibrosis in silicosis—a form of pulmonary fibrosis." (PMID 36738110, 2023).
renal carcinoma (1 paper, 2025). A carcinoma arising from the epithelium of the renal parenchyma or the renal pelvis. "Furthermore, high expression of NR2F1 is associated with tumor relapse and metastasis in salivary adenoid cystic carcinoma, urothelial cancer, and renal cancer models." (PMID 40955663, 2025).
Renal cyst (1 paper, 2024). A fluid filled sac in the kidney. "Both NR2F1 and NR2F2 have been annotated with only six safety alerts, including visual impairment, renal cysts, and a bicuspid aortic valve." (PMID 39065726, 2024).
sensorineural hearing loss (1 paper, 2025). "BBSOAS, caused by haploinsufficiency of the NR2F1 gene, which is critical for auditory system development, is characterized by optic atrophy and often includes sensorineural hearing loss." (PMID 41169613, 2025). "Patients with NR2F1 microdeletions (400–500 kb at or near both breakpoints) on the 5q15 region often exhibit severe congenital sensorineural hearing loss and elevated ABR thresholds, especially at lower frequencies, despite having a structurally normal cochlea." (PMID 41169613, 2025).
silicosis (1 paper, 2023). Silicosis is a respiratory disease caused by breathing in (inhaling) silica dust. "It is worth noting that transcription factor NR2F1 protein is involved in regulating ECM expression and tissue fibrosis in silicosis." (PMID 36738110, 2023).
triple-negative breast carcinoma (1 paper, 2013). An invasive breast carcinoma which is negative for expression of estrogen receptor (ER), progesterone receptor (PR), and human epidermal growth factor receptor 2 (HER2). "Placement of the Mcs1a-orthologous gene desert and NR2F1 within the deletion hotspot suggests that NR2F1 may play a role in deregulation of a fraction of these cell cycle-related genes associated with the triple-negative breast cancer-specific 5q deletions." (PMID 23785296, 2013).
tumor (58 papers, 2011 to 2026). "Others have shown that overexpression of NR2F1 increases invasiveness and metastatic potential in tumor and cancer-associated stromal cells." (PMID 40955663, 2025). "ATF3 directly inhibits AR transcriptional activity and downstream targets (e.g., PSA), while NR2F1 loss promotes tumor heterogeneity and enzalutamide resistance." (PMID 40470696, 2025). "NR2F1 is associated with tumor dormancy in several tumor models, and the BRAFi + MEKi drug-tolerant state exhibits traits similar to cellular dormancy, prompting us to test the link between NR2F1 and targeted therapy response." (PMID 40955663, 2025). "Nuclear Receptor subfamily 2 group F member 1 (NR2F1) is mainly associated with tumour cell dormancy, invasion, and metastasis during cancer development and growth." (PMID 39219375, 2024). "Our data expand this mechanistic analysis by showing that NR2F1 and MenaINV are co-regulated, and that their induction is caused by interaction with tumor-associated macrophages which are enriched in a niche surrounding TMEM doorways." (PMID 35110548, 2022). "The analysis of NR2F1 expression, a critical node in tumor dormancy induction, can potentially differentiate between active occult tumor cells giving a risk for early metastasis development and more long-term quiescent DTCs." (PMID 30322396, 2018). "The T1 and T2 tumor cells were also different in terms of the expression of epithelial markers (EpCam, E-Cadherin), mesenchymal markers (Vimentin, Pdgfra) and dormancy associated marker (Nr2f1) as shown by the qRT-PCR analysis." (PMID 37841442, 2023). "Moreover, NR2F1 as well as RARβ direct the deacetylation of histone H3 by histone deacetylases, which is associated with the presence of dormant disseminated tumor cells in vivo." (PMID 34064392, 2021). "Based on these observations, enhanced migration and release from the dormant state in tumor cells by the loss of NR2F1 may be associated with earlier relapse." (PMID 31146704, 2019). "In addition, NR2F1 protein is a known tumour dormancy marker in cancer‐associated fibroblasts." (PMID 36738110, 2023). "JUN, FOS, STAT3, JUND and NR2F1 were up-regulated in clusters C2 and C3, leading to tumor progression and immune evasion by influencing target genes HSPA1A, CXCL9 and PDGFR." (PMID 42074110, 2026). "NR2F1 has been previously reported to induce tumor dormancy and inhibit mTOR signaling in several cancer models." (PMID 40955663, 2025). "NR2F1 over-expression was sufficient to reduce BRAFi + MEKi effects on tumor growth in vivo, and cell proliferation, death, and invasion in vitro." (PMID 40955663, 2025). "Both in vitro and in vivo results showed a higher tumor growth rate in NR2F1-overexpressing cells following BRAFi + MEKi treatment." (PMID 40955663, 2025). "Dormancy indicators, including NR2F1, decreased Ki-67, and autophagy-related proteins, are present in disseminated tumor cells (DTCs) from patients with extended disease-free periods, indicating their dormant condition." (PMID 41465319, 2025). "Upon reaching MRD when tumors expressed high NR2F1 levels and tumor size was stable for several weeks, rapamycin was given in combination with BRAFi + MEKi." (PMID 40955663, 2025). "Under the pharmacologic activation of the transcriptional factor NR2F1, a master regulator of tumor cell dormancy, cancer cells acquire a dormant phenotype associated with the inhibition of cell cycle progression and mTOR signaling." (PMID 38418814, 2024). "Proliferation and tumor studies exhibited a decrease in growth and an upregulation of dormancy markers, such as NR2F1 and CDKN1B." (PMID 39199676, 2024).